GTF2IRD1 (GTF2I repeat domain containing 1)
Description:
May be a transcription regulator involved in cell-cycle progression and skeletal muscle differentiation. May repress GTF2I transcriptional functions, by preventing its nuclear residency, or by inhibiting its transcriptional activation. May contribute to slow-twitch fiber type specificity during myogenesis and in regenerating muscles. Binds troponin I slow-muscle fiber enhancer (USE B1). Binds specifically and with high affinity to the EFG sequences derived from the early enhancer of HOXC8 (By similarity).
Synonyms: CREAM1; GTF3; MUSTRD1; RBAP2; WBSCR11; WBSCR12; BEN; WBS; hMusTRD1alpha1
Tractability: PROTAC: UniProt records ubiquitination sites on it; ubiquitination databases record sites on it.
Gene: Protein-coding gene on chromosome 7 (74,452,463 to 74,602,619, forward strand). Ensembl gene ENSG00000006704.
Subcellular location: Nucleus
Subcellular location (Human Protein Atlas): Nucleoplasm; Cytosol
Gene Ontology:
Molecular function: DNA-binding transcription repressor activity, RNA polymerase II-specific; protein binding; RNA polymerase II cis-regulatory region sequence-specific DNA binding; DNA-binding transcription factor activity; DNA-binding transcription factor activity, RNA polymerase II-specific
Biological process: negative regulation of transcription by RNA polymerase II; regulation of DNA-templated transcription; transcription by RNA polymerase II
Cellular component: nucleoplasm; nucleus
Genetic constraint (gnomAD): Loss-of-function variants: 15 observed, 74.68 expected, observed/expected ratio (o/e) 0.2, 90% interval 0.13 to 0.31. The upper end of that interval is the gene's LOEUF score, 0.31, which puts it in group 1 of 6, group 1 being the genes least tolerant of losing a copy. Missense variants: 705 observed, 1,051.1 expected, observed/expected ratio (o/e) 0.67, 90% interval 0.63 to 0.71. Synonymous variants: 396 observed, 446.14 expected, observed/expected ratio (o/e) 0.89, 90% interval 0.82 to 0.96.
Homologues: Orthologues: chimpanzee GTF2IRD1 (98% identical), dog GTF2IRD1 (95% identical), pig GTF2IRD1 (95% identical), macaque GTF2IRD1 (92% identical), rabbit GTF2IRD1 (92% identical), guinea pig GTF2IRD1 (88% identical), rat Gtf2ird1 (87% identical), mouse Gtf2ird1 (87% identical), tropical clawed frog gtf2ird1 (65% identical), zebrafish gtf2ird1 (55% identical). Paralogues in human: GTF2I (28% identical), GTF2IRD2 (20% identical), GTF2IRD2B (20% identical), ZMYM4 (12% identical), ZMYM3 (11% identical), ZMYM2 (11% identical), ZMYM6 (9% identical), THAP12 (8% identical), ZMYM1 (7% identical), QRICH1 (7% identical), KIAA1958 (6% identical), EPM2AIP1 (6% identical), and 6 more.
Diseases named in the same sentence as GTF2IRD1 in open-access papers:
GTF2IRD1 is named in the same sentence as 31 diseases in open-access papers, as found by Europe PMC text mining. Sharing a sentence is not in itself a finding about the gene and the disease. The quoted sentences say what the papers report.
Williams syndrome (14 papers, 2012 to 2025). "Williams syndrome is caused by a microdeletion of 26–28 genes on chromosome 7, including GTF2IRD1, which encodes a transcription factor suggested to play a role in the behavioral profile of Williams syndrome." (PMID 37370259, 2023). "GTF2IRD1 is one of the genes implicated in Williams-Beuren syndrome, a disease caused by haploinsufficiency of certain dosage-sensitive genes within a hemizygous microdeletion of chromosome 7." (PMID 23145142, 2012). "This line was created to better understand the effect of loss of the human orthologue of this gene in WBS, which is a neurodevelopmental disorder caused by the hemizygous deletion of GTF2IRD1 and other genes within the Williams-Beuren syndrome critical region of 7q11.23." (PMID 27295951, 2016). "GTF2I and the functionally related GTF2IRD1 are two of up to 28 genes deleted in the microdeletion syndrome Williams-Beuren Syndrome (WS; OMIM #194,050)." (PMID 39136782, 2024). "GTF2IRD1 has been reported as one of the promising genes for Williams syndrome (WS), particularly responsible for neurodevelopmental abnormalities, which is known as a risk factor for suicidal behavior." (PMID 31476763, 2019). "GTF2IRD1 is one of 28 genes that are located in 1.5-Mb region on chromosome 7q11.23 that is commonly deleted in Williams syndrome." (PMID 26884464, 2016). "However, we report on two nominally significant SNPs in two genes that have been implicated in the cognitive and social phenotypes of Williams syndrome, BAZ1B and GTF2IRD1." (PMID 30008175, 2018). "GTF2I codes for the transcription factor TFII-I that is highly expressed in the brain, and it belongs to a small paralogous gene family of transcriptional regulators that includes two other genes in the Williams-syndrome region, GTF2IRD1 and GTF2IRD2 that interact with one another in their effects." (PMID 25429715, 2014). "Studying rare events that result in atypical deletions sparing different genes in the Williams syndrome critical region (WSCR), as well as single gene knock out studies in mouse models, have suggested that GTF2IRD1 and BAZ1B play a role in the craniofacial abnormalities." (PMID 30008175, 2018).
colorectal cancer (3 papers, 2019 to 2021). A primary or metastatic malignant neoplasm that affects the colon or rectum. "Previous oncology studies about GTF2IRD1 have been conducted in only three cancers, including colorectal cancer, breast cancer, and retinoblastoma." (PMID 32936232, 2020).
Anxiety (2 papers, 2019 to 2023). Intense feelings of nervousness, tension, or panic often arise in response to interpersonal stresses. "The associations of GTF2IRD1 with anxiety and social impairment in WS have been previously reported." (PMID 31476763, 2019). "Thus, we thoroughly assessed non‐social anxiety‐like features in the CD mouse model to identify tasks sensitive to this mutation and evaluate the potential impact of Gtf2ird1." (PMID 37370259, 2023). "However, it does appear to mediate aspects of light‐induced anxiety‐related behaviors and sensorimotor coordination, as complementation can ameliorate the deficits observed in the CD mice, suggesting a role for Gtf2ird1 in sensorimotor processing." (PMID 37370259, 2023). "Specifically, the WSCR regulates social motivation along with motor and anxiety phenotypes, but Gtf2ird1 complementation is not sufficient to rescue most of these traits." (PMID 37370259, 2023).
Intellectual disability (2 papers, 2022 to 2024). "This may be because the genes GTF2I and GTF2IRD1 mainly affect the neurodevelopment related to these two functional regions, but they are not sufficient to cause the intellectual disability symptoms typical for WBS patients." (PMID 35379245, 2022).
adenoma (1 paper, 2021). A neoplasm arising from the epithelium. "Immunohistochemistry validation showed that GTF2IRD1 enhanced significantly throughout the mucosa-adenoma-carcinoma sequence, while SPIB and NR3C2 kept decreasing in stroma during the disease course." (PMID 34094897, 2021). "Additionally, GTF2IRD1 expression also increased in the sequence of mucosa-adenoma-tumor." (PMID 34094897, 2021).
autism (1 paper, 2020). Persistent deficits in social interaction and communication and interaction as well as a markedly restricted repertoire of activity and interest as well as repetitive patterns of behavior. "One possible genetic link to serotonergic disruption of the amygdala is GTF2IRD1, a general transcription factor included in the WS deletion that is linked to the characteristic WS behavioral phenotype and also implicated as a common site of allelic variation in autism." (PMID 32024554, 2020). "In addition to GTF2IRD1, several other genetic polymorphisms linked to ASD are found in genes involved in serotonin transporter signaling and function, and high concentration of serotonin in the blood, called hyperserotonemia, occurs in about one third of autism cases." (PMID 32024554, 2020).
cognitive delay (1 paper, 2014). "LIMK1, GTF2I and GTF2IRD1 genes have been related to aspects of cognitive delay." (PMID 25016475, 2014).
colorectal adenoma (1 paper, 2021). An adenoma that arises from the colon or rectum. "Notably, six DE-TFs, DACH1, GTF2IRD1, MEIS2, NR3C2, SOX9, and SPIB, were identified as having a dynamic signature along the colorectal adenoma-carcinoma sequence." (PMID 34094897, 2021).
microcephaly (1 paper, 2021). A congenital or acquired developmental disorder in which the circumference of the head is smaller than normal for the person's age and sex. "GTF2I and GTF2IRD1 heterozygotes exhibit microcephaly and neural defects." (PMID 33859276, 2021).
pancreatic adenocarcinoma (1 paper, 2020). "Through pathway function enrichment analysis, we found that GTF2IRD1 expression was positively correlated with pancreatic adenocarcinoma pathway and TGF-β signaling pathway." (PMID 32936232, 2020). "Furthermore, pathway enrichment analysis showed that GTF2IRD1 may be involved in pancreatic adenocarcinoma pathway, TGF-β signaling pathway, T-cell receptor signaling pathway, leukocyte transendothelial migration, resistin as a regulator of inflammation." (PMID 32936232, 2020).
pancreatic cancer (1 paper, 2020). "However, the potential function of GTF2IRD1 in pancreatic cancer (PC) still remains unknown." (PMID 32936232, 2020).
retinoblastoma (1 paper, 2014). A malignant tumor that originates in the nuclear layer of the retina. "The protein encoded by GTF2IRD1 contains five GTF2I-like repeats and functions as a transcription factor or as a positive transcriptional regulator under the control of the Retinoblastoma protein." (PMID 25105779, 2014).
systemic lupus erythematosus (1 paper, 2019). An autoimmune multi-organ disease typically associated with vasculopathy and autoantibody production. "Genome-wide association studies of systemic lupus erythematosus (SLE) in Chinese and Korean populations demonstrated strong association of single nucleotide polymorphisms (SNPs) located in the GTF2I-NCF1 region, rs73366469 (GTF2I), rs117026326 (GTF2I), rs80346167(GTF2IRD1) and rs201802880 (NCF1)." (PMID 31705128, 2019).
cancer (6 papers, 2019 to 2021). A tumor composed of atypical neoplastic, often pleomorphic cells that invade other tissues. "Recent findings have discovered novel oncogenes on chromosome 7 (e.g., GTF2IRD1 and PEG10) associated with progression in other cancer types." (PMID 34885165, 2021). "Knockdown of GTF2IRD1 expression inhibited cancer cell proliferation, colony formation, and invasion in vitro." (PMID 32936232, 2020). "Three genes (NFE2L3, GTF2IRD1, and PPM1H) were significantly differentially expressed between cancer and normal cells or between cancer and IBDs with greater than 2-fold changes (all P < 0.001)." (PMID 30988394, 2019).
tumor (6 papers, 2009 to 2021). "Possible associations between GTF2IRD1 expression and tumor immunity were analyzed using ESTIMATE algorithm and single-sample Gene Set Enrichment Analysis (ssGSEA)." (PMID 32936232, 2020). "All these findings supported the role of GTF2IRD1 overexpression in suppressing the infiltration and anti-tumor effect of CD8+ T cells, although the underlying mechanism needs to be further studied." (PMID 32936232, 2020). "The GTF2IRD1 gene encodes a transcription factor protein, that are related to tumor-promotion." (PMID 30940089, 2019). "In addition, paired differential expression analysis based on GSE28735 dataset demonstrated the expression GTF2IRD1 was up-regulated in PC tissues compared with that in the adjacent non-tumor tissues (P-value <0.0001)." (PMID 32936232, 2020). "Consistently, ESTIMATE algorithm also demonstrated that high expression of GTF2IRD1 was correlated with high tumor purity and low immune score, indicating that GTF2IRD1 overexpression may induced immune suppression in PC." (PMID 32936232, 2020). "And GTF2IRD1 overexpression promotes tumor progression and correlates with less CD8+ T-cells infiltration, which might be a novel therapeutic target in PC." (PMID 32936232, 2020). "Therefore, we hypothesized that GTF2IRD1 expression could be a potential marker for decreased TIL infiltration in the tumor immune microenvironment." (PMID 32936232, 2020). "Thus, we proposed that GTF2IRD1 overexpression promoted tumor progression in PC." (PMID 32936232, 2020). "To further evaluate the functional role of GTF2IRD1 in tumor cells proliferation and invasion, we transfected PANC-1 and AsPC-1 cells with si-GTF2IRD1." (PMID 32936232, 2020). "ESTIMATE algorithm demonstrated that GTF2IRD1 expression positively correlated with tumor purity (Cor = 0.40, P<0.0001), while negative correlated with immune score (Cor = −0.36, P<0.0001) in the TCGA PC cohort." (PMID 32936232, 2020).
neurodevelopmental disorder (2 papers, 2012 to 2016). A behavioral and cognitive disorder with onset during the developmental period that involves impaired or aberrant development of intellectual, motor, or social functions. "Although no in vivo neuronal targets of GTF2IRD1 were detected, possible GTF2I targets included genes involved in axon guidance, neurodevelopmental disorders, calcium signaling, cell cycle, and immune response." (PMID 23118870, 2012).
GTF2IRD1 also shares sentences with these, for which no sentence is quoted: Cognitive impairment (2 papers); ovarian carcinoma (2); Andersen syndrome (1); bladder cancer (1); breast carcinoma (1); central nervous system cancer (1); esophageal cancer (1); genetic disorder (1); leukemia (1); lung carcinoma (1); Neurodevelopmental delay (1); rectal adenocarcinoma (1); thyroid cancer (1); Turner syndrome (1); Vascular Ehlers Danlos syndrome (1).